NAMPT (nicotinamide phosphoribosyltransferase)
Diseases named in the same sentence as NAMPT in open-access papers (continued):
Sharing a sentence is not in itself a finding about the gene and the disease.
cancer (continued). "Further support is brought by a patent that discloses chemical compounds that inhibit NAPRT activity (including some non-steroidal anti-inflammatory drugs) and sensitize cancer cells to NAMPT inhibitors." (PMID 32477131, 2020). "Cancers arising from tissue with a highly NAPRT are expression completely and irreversibly dependent on the NAPRT-regulated de novo pathway, while cancers deriving from tissues with the low level of NAPRT mainly rely on the NAMPT-mediated NAD+ salvage pathway." (PMID 33028824, 2020). "The purpose of this review is to describe the impact of NAMPT and NAMPT inhibition on the non-energetic cellular functions of NAD+ in cancer cells." (PMID 32010616, 2019). "Additionally, to clarify the function of extracellular NAMPT in cancer cell proliferation, we conducted an immunohistochemical analysis of PCNA and intracellular and extracellular NAMPT, which showed consistent results." (PMID 31817697, 2019). "Therefore, inhibition of NAMPT and reduction of Nicotinamide adenine dinucleotide (NAD) synthesis is one strategy for cancer therapy." (PMID 31817697, 2019). "Both cancer cell lines developed resistance to FK866, and interestingly, in both cases, acquired resistance was independent of mutations in NAMPT but rather relied on the activation of alternative metabolic pathways that compensated for low NAD(H) level." (PMID 29541451, 2018). "Recently, several NAMPT inhibitors have been synthesized, and some of them were tested in clinical trials among patients with cancers that are nonresponsive to conventional therapy." (PMID 29546048, 2018). "NAMPT inhibition is specifically effective in cancer cells in which NAPRT-mediated NAD+ production is not functioning." (PMID 29541451, 2018). "Nicotinamide phosphoribosyltransferase (NAMPT), the rate-limiting enzyme in NAD+ biosynthesis from nicotinamide, is one of the major factors regulating cancer cells metabolism and is considered a promising target for treating cancer." (PMID 26542945, 2015). "It was recently demonstrated that NAMPT inhibition attenuates glyceraldehydes-3-phosphate dehydrogenase activity, which in turn affects glycolysis, the pentose phosphate pathway, and the TCA cycle and their downstream pathways in cancer cells." (PMID 25486521, 2014). "Over-expression of NAMPT is believed to activate nicotinamide adenine dinucleotide (NAD) salvage pathway and raise NAD+ level to provide sufficient energy for the survival of rapidly proliferating cancer cells." (PMID 24690091, 2014). "In contrast to findings in other cancer cell types, we found that hepatocarcinoma cells express lower levels of NAMPT compared to non-cancerous primary hepatocytes." (PMID 24603648, 2014). "Suppressing NAMPT-mediated NAD + synthesis by chemotherapeutic agents in cancer cells may also suppress non-cancerous cells, especially brain tissues." (PMID 40085284, 2025). "The poor efficacy of NAMPT inhibitors may result from the nonenzymatic activity of NAMPT and the cancer-promoting activity of extracellular NAMPT (eNAMPT), which is a cytokine-like protein." (PMID 40486861, 2025). "The tumor-promoting effect of CANA at low concentrations observed in our study may hinder in vivo animal examinations as a next step for its application in cancer chemotherapy; however, this may be overcome by agents that inhibit the NAD+ salvage pathway, such as NAMPT inhibitors." (PMID 39940750, 2025). "Interestingly, according to a previous study, NAMPT inhibition was reported to be cytotoxic in cancer cell lines in vitro but not in non-cancer cells." (PMID 40280967, 2025). "In addition, high levels of NAMPT and NT5E are predictive of shorter survival times in patients with GBM, indicating that they may support the survival and/or growth of cancer in the brain (p < 0.05)." (PMID 38893173, 2024).
cancer (continued). "At first glance, it may seem that effective targeting of NAMPT and NAD biosynthesis in cancer cells whilst sparing healthy tissues would be a particularly difficult task, especially with the presence of numerous other pathways through which NAD levels can be restored." (PMID 38893173, 2024). "In principle,decreasing the intracellular levels of NAD+ in U87MG cellsby NAMPT inhibitors may be effective and harm the cells if no extracellularNAD+ can be taken up by the cancer cells." (PMID 38924492, 2024). "It has been shown that the use of inhibitors of nicotinamide phosphoribosyltransferase (NAMPT) can reduce NAD+ levels by inhibiting energy metabolism pathways like glycolysis, citric acid cycle and oxidative phosphorylation (OXPHOS), contributing to a decrease in cancer proliferation." (PMID 38999946, 2024). "Additionally, NAMPT-specific inhibitors lower NAD+ levels and the activity of metabolic pathways including glycolysis, the citric acid cycle, and OXPHOS, thereby helping to suppress cancer cell proliferation." (PMID 39272943, 2024). "Cancer cells, which are marked by a heightened need for NAD to fuel their reprogrammed energy metabolism, rely on a sustained NAM salvage pathway through the increased expression and activity of the rate-limiting enzyme nicotinamide phosphoribosyltransferase (NAMPT)." (PMID 37259338, 2023). "Based on the NAMPT inhibitor CHS828 and EGFR inhibitor erlotinib, a compound 28 lacking the Michael receptor with a good double inhibitory effect were screened through the fusion of pharmacophore to inhibit the proliferation of several cancer cell lines in vitro." (PMID 35906622, 2022). "Failure of NAMPT inactivation is also explained by the presence of alternative sources of NAD+ with the nicotinate phosphoribosyltransferase (NAPRT), which catalyzes the first step of NAD+ biosynthesis from nicotinic acid (the Preiss–Handler pathway), frequently active in cancer cells." (PMID 35681770, 2022). "Furthermore, NAMPT-specific inhibitors reduce NAD+ levels by inhibiting energy metabolism pathways such as glycolysis, citric acid cycle, and OXPHOS, contributing to the suppression of cancer cell proliferation." (PMID 33609766, 2021). "Systematic exploration of NAM and its metabolites MNAM, 2PY, and 4PY in cancer, related to the expression of not only NNMT, but also NAMPT (the rate-limiting enzyme in NAD+ salvage pathway) and AOX1 (oxidizes MNAM to 2-PY and 4-PY), may provide a better insight into their function." (PMID 34073600, 2021). "However, this response to NAMPT inhibition is not a universal feature of tumor cells; that is, not all cancer cells exhibit an increase in ROS or NAD+ depletion upon NAMPT inhibition." (PMID 33384409, 2021). "Therefore, targeting NAMPT in tumors lacking NAPRT has been identified as an anti-cancer drug target." (PMID 32111066, 2020). "Moreover, NAMPT-specific inhibitors may deplete the NAD levels and restrain the cancer cell proliferation by inhibition of the energy production." (PMID 31750245, 2019). "Therefore, we suppose that co-administration of NAMPT inhibitor and NAPRT inhibitor may effectively decrease NAD levels and kill cancer cells." (PMID 31448236, 2019). "Although HMGA2 silencing did not change the steady‐state cellular NAD+ levels in our cell models (data not shown), higher NAMPT protein levels in HMGA2+ cancer cells allow for expedient replenishing of NAD+ substrate to facilitate a strong DNA stress‐induced PARylation response." (PMID 30289618, 2019). "The mechanism by which NAMPT overexpression occurs in cancer is not fully elucidated." (PMID 31645844, 2019). "An understanding of the non-metabolic implications of NAMPT inhibition may uncover additional targetable vulnerabilities, providing combinatorial opportunities for therapeutic intervention in cancer." (PMID 32010616, 2019).
cancer (continued). "Interestingly, expression of NAPRT, which differs across cancer cell lines, correlates with EMT status, and may be related to the differential effects of NAMPT inhibition on EMT." (PMID 32010616, 2019). "Based on our results, we cannot rule out the possibility that NAMPT inhibition may trigger other types of cell death in other cancer cells." (PMID 31803365, 2019). "So far, there are no data available on cancer stem cells regarding NAMPT inhibitors." (PMID 26040985, 2015). "Insight into the mechanism behind NAMPT role in tumorigenesis led to the development of specific NAMPT inhibitors that might have a future role in adjuvant therapeutic modalities in cancers not responding for the conventional therapy." (PMID 25946974, 2015). "Using high throughput screening system targeting NAMPT, we obtained a potent NAMPT inhibitor MS0 (China Patent ZL201110447488.9) with excellent in vitro activity (IC50 = 9.87 ± 1.15nM) and anti-proliferative activity against multiple human cancer cell lines including stem-like cancer cells." (PMID 26040985, 2015). "However, our data give evidence that resveratrol regulates NAMPT activity in cancer cells and non-cancerous cells." (PMID 24603648, 2014). "Moreover, little is known about NAMPT and SIRT1 regulation by resveratrol in cancer cells." (PMID 24603648, 2014). "Interestingly, altered NAMPT levels have been implicated in metabolic disorders and cancer, and FK866, a highly specific NAMPT inhibitor that abolishes NAD+ circadian oscillations and thereby SIRT1 cyclic activity, is used to control cell death in human cancer tissues." (PMID 22834651, 2012). "Visfatin, known as pre-B cell colony-enhancing factor (PBEF) or nicotinamide phosphoribosyltransferase (NAMPT), could be expressed in various tissues and involved in the pathogenesis of a wide range of diseases, such as CVD, metabolic and inflammatory disorders, cancers and aging." (PMID 37180779, 2023). "Interestingly, not all cancer cells exhibit an increase in ROS upon inhibition of NAMPT." (PMID 32010616, 2019). "Interestingly, NAMPT inhibition alone may not always have impact on cancer cell survival despite their elevated NAMPT expression." (PMID 30856230, 2019). "ASCs with TRAF3IP2 knockdown (ASCTRAF3IP2KD) did not exhibit changes in TRAF3IP2, NAMPT or SIRT1 levels, indicating a cancer-specific effect of TRAF3IP2 silencing." (PMID 41436543, 2025). "Here, we demonstrated a negative correlation between the expression of NAMPT, an NAD+ metabolism enzyme, and PD-L1 expression in various cancer cell lines." (PMID 38448544, 2024). "While in tumors, NAMPT is ubiquitously expressed, NAPRT expression levels were found to be largely variable with several cancer cell lines showing either marginal or no NAPRT expression and many other cell lines exhibiting high NAPRT levels." (PMID 38396769, 2024). "Thus, some sporadic cases may be vulnerable to NAMPT inhibition, regardless of cancer type." (PMID 38092728, 2023). "Indeed, cancer cells expressing high levels of NAPRT are resistant to NAMPT inhibitors and both the silencing of the gene and chemical inhibition of the enzyme overcome such resistance, suggesting that the coadministration of NAPRT and NAMPT inhibitors might improve anticancer therapies." (PMID 36770640, 2023). "Another group postulated that oncosis is the critical pathway leading to cancer cell death in response to the NAMPT inhibitor, GNE-617, in several non-hematological cancer cell lines irrespective of the appearance of signs of apoptosis or autophagy." (PMID 34068917, 2021). "Our group showed previously that NAMPT is an important metabolic target in PDAC, and FK866, a non-competitive inhibitor of this enzyme, decreases cancer cell viability in vitro and in vivo." (PMID 29156703, 2017).
cancer (continued). "Elevated SIRT1 expression was found in hepatocarcinoma cells when compared to non-cancerous hepatocytes, and NAMPT inhibition led to cell death via the AMPK/mTOR pathway, offering a novel strategy to prevent cancer cell growth in vivo." (PMID 28160567, 2017). "Unlike classical cytotoxic agents targeting mitosis or DNA, NAMPT inhibitors induce tumor cell death by depleting NAD+ levels, leading to metabolic catastrophe and apoptosis, with activity observed even in slowly proliferating cancer cells." (PMID 40872592, 2025). "However, other studies have shown that some cancer cell lines, including GBM, can be rescued from NAMPT inhibition by the addition of QA, but not tryptophan, which is the first step in the kynurenine pathway." (PMID 38893173, 2024). "Furthermore, a specific noncompetitive inhibitor for NAMPT, FK866, showed significant induction of delayed cell death in human HepG2 cells, indicating a potentially novel approach for triggering apoptosis in cancer cells." (PMID 35565188, 2022). "Interestingly, the functional significance of NAMPT on sirtuins is likely cancer cell type specific, since changes in SIRT1 expression with NAMPT inhibition have not been observed in all NAMPT inhibitor-sensitive cells." (PMID 32010616, 2019). "In conclusion, it is critical to understand the impact of NAMPT and NAMPT inhibitors on both the energetic and the non-energetic cellular functions of NAD+ in cancer as these insights may be key to future development of this class of agents." (PMID 32010616, 2019). "We have chosen two human cancer cell lines that differ in the way they use nicotinic acid and nicotinamide for NAD formation, assuming that the addition of nicotinic acid to the growth medium can abolish NAMPT inhibition in one cell line but not in the other." (PMID 25486521, 2014). "Inhibitors of nicotinamide phosphoribosyltransferase (NAMPT) are promising cancer drugs currently in clinical trials in oncology, including APO866, CHS-828 and the CHS-828 prodrug EB1627/GMX1777, but cancer cell resistance to these drugs has not been studied in detail." (PMID 21144000, 2010).
tumor (266 papers, 2009 to 2026). "NAMPT is also highly expressed in a distinct subset of tumor-associated macrophages (TAMs) with immunosuppressive activity." (PMID 40775221, 2025). "Similar to that of PD‐L1, NAMPT expression correlated with tumor stage, and high NAMPT levels were associated with poor survival." (PMID 39988985, 2025). "Macrophage NAMPT expression within the tumour microenvironment has been associated with cancer, but with differing conclusions." (PMID 40751253, 2025). "Using single‐cell RNA sequencing (scRNA‐seq) data, it is founded that NAMPT is highly expressed in SPP1+ tumor‐associated macrophages (TAMs), a unique subset of TAMs associated with immunosuppressive activity." (PMID 38308188, 2024). "This binding enhances the expression of NAMPT, leading to aerobic glycolysis that promotes the expression of pro-inflammatory genes in tumor-associated macrophages (TAM) stimulated with IFN-γ." (PMID 38605962, 2024). "Together, KPT-9274 is a selective NAMPT inhibitor that causes a multifaceted anti-tumor effect against NAMPT-dependent cell lines." (PMID 38424218, 2024). "NAMPT plays a pivotal role in Tumor‐associated macrophages (TAMs) reprogramming by regulating the HIF‐1α/STAT3 and a reduction in STING activation." (PMID 38308188, 2024). "This treatment approach was indeed successful in several NAPRT-deficient tumor models, expanding the therapeutic window of NAMPT inhibitors and mitigating toxicity." (PMID 38396769, 2024). "Our previous work identified that IFNγ upregulates NAMPT in tumor-associated macrophages and is important for their anti-tumorigenic function." (PMID 36900204, 2023). "On the other hand, the reduction in NAMPT expression causes a decrease in the proliferation rate, clone and tumorsphere formation, competition with other cells, in vivo proliferation and tumor formation in xenografts." (PMID 36864434, 2023). "NAMPT levels are often significantly elevated in a number of tumor types, are associated with advanced tumor progression, and can be induced by hypoxia, which is another marker of poor prognosis." (PMID 37583931, 2023). "Because of the unique and extensive effects of NAMPT in cells, the development of inhibitors with dual targeting functions can improve the anti-tumor efficacy and reduce the side effects caused by the drug alone, which is a promising therapeutic strategy." (PMID 35906622, 2022). "For example, a team studied the contribution of NAMPT to tumor-associated neutrophils tumorigenic transformation." (PMID 35906622, 2022). "Several polymorphisms were identified in NAMPT in a study screening normal and tumor samples from different tissues and populations." (PMID 35565188, 2022). "The first finding of this work is that tumor samples carrying BRAF-mutations over-express NAMPT, as demonstrated by analyzing the TCGA dataset, and MM and THC tissue microarrays." (PMID 35272691, 2022). "It was shown that NAMPT expression in pro-angiogenic neutrophils is significantly upregulated and that the inhibition of NAMPT by the small molecule inhibitor FK866 impaired the pro-angiogenic phenotype of such tumor-associated neutrophils." (PMID 35158807, 2022). "Lastly, it has been recently shown that NAMPT is critical for the pro-angiogenic activity of tumor-associated neutrophils (TANs)." (PMID 32477131, 2020). "As neutrophils play a crucial role during tumor development, we focused on the regulation of NAMPT signaling and functionality of neutrophils in IFN deficiency." (PMID 31717318, 2019). "Previously, we have observed that NAMPT signaling promotes pro-tumoral bias of tumor-associated neutrophils." (PMID 31717318, 2019). "Here, we have screened normal and tumor samples from different tissues and populations of origin for mutations in human NAMPT and NAPRT1, and evaluated their potential pathogenicity." (PMID 25201160, 2014). "NAMPT deficiency impaired NK cell anti-tumor immunity and accelerated tumor growth." (PMID 40775221, 2025).